IRAK1 (interleukin 1 receptor associated kinase 1)
Diseases named in the same sentence as IRAK1 in open-access papers (continued):
Sharing a sentence is not in itself a finding about the gene and the disease.
Sepsis (33 papers, 2012 to 2025). Sepsis is defined as life-threatening organ dysfunction caused by a dysregulated host response to infection. "IRAK1 deficiency has been shown to attenuate early-phase cytokine responses in polymicrobial sepsis models, significantly improving survival rates (35% vs. 85% mortality in wild-type mice)." (PMID 40509176, 2025). "Multiple clinical studies have found that polymorphisms of the IRAK1 gene are associated with prognosis in sepsis patients." (PMID 36091017, 2022). "Previous animal experiments revealed functional variability in cellular mosaicism for IRAK1 expression and natural X-linked polymorphisms during sepsis." (PMID 34531808, 2021). "IRAK1 deficient mice have significantly increased survival relative to wild type (WT) mice in polymicrobial sepsis, and IRAK1 knockout mice treated with LPS had significantly less liver and kidney damage than did WT mice." (PMID 30279971, 2018). "Supporting this idea, it was also found that IRAK1-deficient mice exhibit markedly lower levels of interleukin- (IL-) 6 and IL-1β and suffer from significantly less sepsis-induced mortality." (PMID 28680194, 2017). "Interleukin-1 receptor-associated kinase 1 haplotype is one of the primary candidate gene contributing to sex-related outcome differences following trauma and sepsis." (PMID 29180997, 2017). "Provided this is true, how this finding is an immune advantage for female neonates remains to be reconciled with previous reports arguing that the upregulation of IRAK-1 is associated with a severe inflammation while its downregulation improved sepsis." (PMID 29321783, 2017). "In this setting, previous genetic studies on several gain of function SNPs in genes of receptors and signaling molecules upstream of NF-κB, such as TLR1 and IRAK1, showed a significant association with severity of sepsis." (PMID 27059500, 2016). "MiR-146b, targeting interleukin (IL)-1 receptor-associated kinase (IRAK1), could reduce sepsis-associated acute kidney." (PMID 34754625, 2021). "Thus, data, although limited, suggest that suppression IRAK1 pathway activation occurs during sepsis and over-activation can be associated with deleterious consequences." (PMID 30279971, 2018). "Notably, mosaicism of IRAK-1 expression in mice results in an immune cell deficiency leading to an improved sepsis outcome, as in IRAK-1-deficient mice." (PMID 29321783, 2017). "Finally, genetic studies of patients with sepsis uncovered an IRAK1-1595C/T polymorphism for which the T haplotype was associated with greater NF-κB nuclear translocation upon ex vivo LPS stimulation, more severe organ dysfunction, the need for longer ventilation, and higher mortality." (PMID 30279971, 2018). "A significant increase regarding the expression of IRAK1 was observed in the lungs of septic mice between 24 h and 48 h after the onset of sepsis." (PMID 40076895, 2025). "PD-1 expression was significantly correlated with PDL-1 and IRAK-1 expression in the S24 group, which was expected considering their role in sepsis response." (PMID 40076895, 2025). "The selective inhibition of IRAK1 appears to be a promising strategy, especially for diseases such as sepsis and ABC-DLBCL." (PMID 38792088, 2024). "Some notable results were published that miR-146a downregulates IRAK1 and other cytokines in LPS-induced immune, inflammation, or sepsis responses, demonstrating the direct relationship between miR-146a and IRAK1." (PMID 38792088, 2024). "In sepsis-related studies, IRAK1 knockout mice showed less inflammation and higher survival rates than normal control mice." (PMID 36091017, 2022). "Another study also found that miRNA-146a diminishes sepsis-induced cardiomyocyte apoptosis and infiltration of inflammatory monocyte cells by inhibiting the same molecule (i.e., IRAK1 and TRAF6)." (PMID 35345264, 2022).
Sepsis (continued). "Human umbilical cord MSC-derived exosomes (hucMSC-Ex) inhibited NF-κB activity via the miR-146b/IRAK1 axis, attenuated sepsis-related acute kidney injury and improved survival in mice with sepsis." (PMID 36579343, 2022). "Treatment with hucMSC-Ex improved survival in mice with sepsis by reducing levels of IRAK1, increasing of miR-146b level, and inhibition of NF-κB activity." (PMID 34956235, 2021). "We also found that in comparison to the untreated sepsis group, narciclasine treatment reduced the protein expression of MyD88, IRAK-1 and TRAF-6 in the livers of septic neonatal rats." (PMID 32076015, 2020). "Lentivirus-expressing miR-146a delivered into the myocardium reduced IRAK1 expression and protected against cardiac dysfunction relative to untransfected mice in a murine model of polymicrobial sepsis." (PMID 30279971, 2018). "In these sepsis studies, IRAK1-mosaic females were merged with the WT group, therefore, the effects of mosaicism remained elusive." (PMID 29180997, 2017). "For instance, SNPs in TLRs, TIRAP, IRAK1, IκB and NF-κB inducing kinase (NIK) genes have been associated with severity of sepsis." (PMID 27059500, 2016). "Our results support this view and show that deregulated miR-146a negatively regulated its target molecules TRAF-6 and IRAK-1 in severe sepsis patients." (PMID 24701036, 2014). "The relative expression levels of TRAF-6 and IRAK-1 were significantly higher in patients with severe sepsis compared to those of the healthy controls (P < 0.0001 and P = 0.0078, resp)." (PMID 24701036, 2014). "Our study showed similar results; the downregulation of miR-146a expression was accompanied by the upregulation of TRAF-6 and IRAK-1 in severe sepsis patients." (PMID 24701036, 2014). "Fourteen tag single nucleotide polymorphisms (tagSNPs) in MyD88, IRAK1, IRAK4 and TRAF6 were genotyped in samples of sepsis-induced ALI (n = 272) and sepsis alone patients (n = 276), and tested for association in this case-control collection." (PMID 22901274, 2012). "Two studies showed that a haplotype in IRAK-1, which increased nuclear levels of NF-κB, was related to severity and mortality of sepsis." (PMID 22901274, 2012). "In addition, miR-146, which is strongly reduced in sepsis, is well known for its anti-inflammatory properties by negatively regulating NF-kB activities and by directly targeting IRAK-1 and TRAF6." (PMID 33362557, 2020). "Since the discovery of IRAK1 in 1996, preclinical studies have established its involvement in a spectrum of inflammatory diseases, including fibrotic diseases, metabolic disorders, arthritis, lupus, and sepsis." (PMID 30279971, 2018). "Modulation of signaling through IRAK1 may be beneficial in human sepsis, a condition considered a global health priority responsible for more than 5 million deaths per year worldwide." (PMID 30279971, 2018). "To test this hypothesis, we conducted a case-control study using tag SNP approach to investigate the association of variants in MyD88, IRAK1, IRAK4 and TRAF6 with susceptibility and outcome of sepsis-induced ALI in Chinese Han population." (PMID 22901274, 2012). "However, redundant signaling pathways may compensate for IRAK1 absence at later stages, underscoring the importance of early intervention in sepsis management." (PMID 40509176, 2025). "The IRAK1 gene is the key encoder of the intracellular signaling pathway of TLR/IL-1R and assists the recognition of viruses by TLR7/8 and the production of IFN- α, being one of the main genes that contribute to the divergence of responses related to gender after trauma and sepsis." (PMID 33791232, 2021). "Moreover, miR-15a down-regulates the expression level of TLR4 and IRAK1 induced by LPS, which have been more commonly related to Gram-negative sepsis, while our sepsis was all caused by Gram-positive bacteria." (PMID 34441323, 2021).
Sepsis (continued). "Moreover, the expression levels of IRAK1, TRAF6, and miR-146a were also determined in the severe sepsis and healthy subjects to analyze whether these polymorphisms are associated with the expression levels of these cytokines." (PMID 24701036, 2014). "The expression of PD-1; PD-L1; TLR-5, -6, and -9; MYD88; IRAK1; TIRAP; and NFkB was quantified by RT-PCR at 24, 48, and 72 h after CLP-induced sepsis." (PMID 40076895, 2025). "For sepsis, we noticed several inflammatory and immune-related proteins, such as IRAK1, IRAK3, IKBKB, and STAT3, in the network, suggesting overlap of the inflammatory response activated in COVID-19 and sepsis." (PMID 33156843, 2020). "Second, miR-146a protects cardiomyocytes from sepsis-induced cell dysfunction via inhibition of NF-κB activity by targeting TRAF6 and IRAK1." (PMID 30224945, 2018). "In total, 37 patients with severe sepsis and 40 healthy individuals were stochastically chosen to investigate the expression levels of miR-146a, TRAF-6, and IRAK-1 in PBMCs." (PMID 24701036, 2014). "Our study demonstrated that severe sepsis patients expressed lower levels of miR-146a and higher levels of TRAF-6 and IRAK-1 than the healthy controls." (PMID 24701036, 2014). "Nevertheless, our results confirmed that the expression level of miR-146a was significantly lower in severe sepsis patients and was accompanied by higher expression levels of TRAF-6 and IRAK-1 compared to the healthy controls." (PMID 24701036, 2014). "IRAK1 deficiency inhibits early pro‐inflammatory cytokine production following polymicrobial sepsis and affects multiple TLR‐dependent pathways, demonstrating that inhibiting IRAK1 expression may be therapeutic." (PMID 33942523, 2021). "One study has reported that the expression of TNF-α was downregulated in Irak1-deficient macrophages when TLR2 or TLR4 were activated, thereby weakening the response to the lethal effects of sepsis caused by LPS or Gram-negative bacteria." (PMID 34421892, 2021). "Animal studies indicate that inhibition or lack of IRAK1 expression is beneficial in sepsis, burn or endotoxemia." (PMID 29180997, 2017). "Notably, a non-selective IRAK1/4 inhibitor showed similar effects on survival and lung injury in mice with sepsis." (PMID 38792088, 2024). "Moreover, the rs2910164 and rs57095329 SNPs could functionally affect the miR-146a expression levels and the miR-146a could negatively regulate the expression of IRAK1 and TRAF6 in severe sepsis patients." (PMID 24701036, 2014). "Well-documented evidence demonstrates that IRAK1 is one of the central kinases involved in the development of various diseases, such as cancer, metabolic disorders (e.g., diabetes), infection (e.g., sepsis), and non-infectious immune diseases (e.g., systemic lupus erythematous)." (PMID 35345264, 2022).
lupus (31 papers, 2010 to 2026). "A cross of this mutation into the ABIN1(D485N) lupus model suggested that IRAK1 catalytic function affects disease progression independent of the type I IFN pathway." (PMID 35801586, 2022). "Interleukin-1receptor-associated kinase 1 (IRAK1) plays a critical role in systemic lupus erythematosus (SLE)." (PMID 36467552, 2022). "IRAK1 is associated with pediatric systemic Lupus Erythematosus and Lubs X-linked mental retardation syndrome." (PMID 31515286, 2019). "MyD88 forms oligomeric complexes with members of the IL-1 receptor-associated kinases (IRAKs), termed the Myddosome, and lupus in ABIN1[D485N] mice is also prevented by crossing to mice in which IRAK4 or IRAK1 are replaced by kinase-inactive mutants." (PMID 31694920, 2019). "This study also investigated the functional relevance of IRAK1 in 2 congenic mouse models, finding that IRAK1 deficiency abrogated lupus-associated phenotypes." (PMID 30279971, 2018). "Deficiency in type I IFN receptor in NZBWF1 mice and IRAK1 (TLR signaling molecule) in a lupus-susceptible mouse led to reduced lupus disease activity." (PMID 24839407, 2014). "Using the IRAK1-deficient mice, we found that in mice bearing the lupus susceptibility loci, Sle1 or Sle3, IRAK1 deficiency abrogated all lupus-associated phenotypes, including IgM and IgG autoantibodies, lymphocytic activation, and renal disease." (PMID 20981241, 2010). "Because exosomes in the blood might protect miRNAs, the association between circulating exosomal miRNA-146a and lupus proinflammatory genes, such as IRAK1 and TRAF6, was studied in peripheral blood mononuclear cells from people with JSLE." (PMID 38355214, 2024). "However, more convincing data support a role of IRAK1 in rheumatological diseases: IRAK1 single nucleotide polymorphisms are linked to an increased risk of rheumatoid arthritis (RA) and particularly systemic lupus erythematosus (SLE)." (PMID 35801586, 2022). "It has been reported that IRAK1 may be a risk gene with a critical role in the pathogenesis of systemic lupus erythematosus (SLE)." (PMID 24690905, 2014). "The variant IRAK1 has also been shown to be associated with increased susceptibility to systemic lupus erythematosus (SLE) an autoimmune disease affecting predominantly females." (PMID 29180997, 2017). "Rigel Pharmaceuticals has recently started pre-clinical and clinical studies of IRAK1/4 inhibitor R835, demonstrating potential in murine models for multiple inflammatory diseases, including arthritis and lupus." (PMID 39543721, 2024). "Among them, Edecesertib (GS-5718; IRAK4i), Zimlovisertib (PF-06650833; IRAK4i), and R835 (IRAK1/4i) have shown promising effectiveness in murine models of lupus, ex vivo proof-of-mechanism in human PBMCs, and favorable safety in phase I studies." (PMID 38255243, 2024). "Studies have reported that IRAK1 inhibitors can inhibit inflammatory signals in splenic monocytes of lupus mice." (PMID 36467552, 2022). "We previously explored the role of IRAK1 in the NF-κB related pathway from lupus model mice through in vitro experiments." (PMID 32760274, 2020). "Since IRAK1 is considered to be a key gene in the pathogenesis of systemic lupus erythematosus, the pathogenesis of the two diseases is different." (PMID 33294443, 2020). "Thus, in this experiment, we isolated BMDMs of MRL/MP and MRL/lpr lupus mice as research objects and explored the association between the SLE and IRAK1 pathways at the cellular and molecular level." (PMID 32760274, 2020). "The results showed that the protein and mRNA of IRAK1 more obviously changed after JP acted on peritoneal macrophages of lupus mice, to be exact, is to suppress." (PMID 31781262, 2019).
lupus (continued). "Lupus is far more prevalent in women than men and it is, therefore, of interest that the TLR7 and IRAK1 genes are X-linked in both humans and mice." (PMID 31694920, 2019). "Firstly, we found that IRAK1 expression and NF-κB expression were significantly upregulated in peritoneal macrophages from lupus-prone MRL/lpr mice." (PMID 31781262, 2019). "Crossing ABIN1 mice, which have a phenotype similar to human lupus, with mice having catalytically inactive IRAK1 prevented splenomegaly, autoimmunity, and liver and kidney inflammation." (PMID 30279971, 2018). "It prevents an overstimulation of the inflammatory response through its recognised target genes, IRAK-1 and TRAF-6, and its dysregulation is associated with many inflammatory diseases including rheumatoid arthritis (RA) and systemic lupus erythematosus (SLE)." (PMID 28103790, 2017). "At least three of the lupus-associated genes are involved in TLR signaling, including IRF5, IRAK1, and TNFAIP3." (PMID 20886024, 2010). "Our research showed that PF had an influential role in the anti-inflammatory mechanism of MRL/lpr mice, and inhibiting the IRAK1-NF-κB pathway might be a unique and promising treatment strategy for lupus inflammation." (PMID 36467552, 2022). "Assuming that inhibition of IRAK1 activity might relieve inflammation in lupus mouse models, we studied the lipopolysaccharide (LPS)-induced splenocytes, CD4+ T lymphocytes, and pathological symptoms of MRL/lpr mice." (PMID 36467552, 2022). "In kidney-related studies, it was found that the expression of IRAK1 in the peripheral blood of patients with lupus nephritis was increased, and the use of IRAK1 inhibitors could alleviate kidney damage in lupus mice." (PMID 36091017, 2022). "We found that every facet of the lupus phenotype could be prevented by crossing ABIN1[D485N] mice to MyD88 KO mice or to mice expressing kinase-inactive mutants of IRAK4 or IRAK1." (PMID 31615747, 2020). "And this article is to investigate the mechanism of IRAK1 in lupus." (PMID 32760274, 2020). "Because the other components of the Myddosome are IRAK1 and IRAK4 and the inactive pseudokinase IRAK2, we studied whether the loss of IRAK1 or IRAK4 catalytic activity, or IRAK2 function, prevented lupus in ABIN1[D485N] mice." (PMID 27807192, 2016). "Recent studies observed an abnormal expression of IRAK1 in several autoimmune diseases, including systemic lupus erythematosus (SLE) and rheumatoid arthritis (RA)." (PMID 34531808, 2021). "Consequently, we speculated that the suppression of IRAK1 activity might inhibit inflammation in mice models of lupus." (PMID 32760274, 2020). "Recent studies have shown that inhibition of IRAK1 could ameliorate IKBα phosphorylation, which in turn inhibits NF-κB signaling and downstream proinflammatory cytokine production in immunocompetent cells, reducing lupus-related renal damage." (PMID 31781262, 2019). "IRAK1 inhibitors can attenuate NF-κB signaling in spleen mononuclear cells of lupus-prone lpr mice and SLE patients with PBMCs, while it reduces proinflammatory cytokine production in mice." (PMID 31781262, 2019). "The link between IRAK-1 expression and obesity-associated meta-inflammation is also supported by the relationship of IRAK-1 or IRAK-2 with other inflammatory conditions such as lung cancer, systemic lupus erythematosus, Vogt-Koyanagi-Harada (VKH) disease, and Alzheimer’s disease." (PMID 26312071, 2015). "In addition, the absence of IRAK1 reversed the dendritic cell “hyperactivity” associated with lupus." (PMID 20981241, 2010). "From these studies, we have learned about the involvement of TLRs in lupus-prone mouse models, the association of polymorphisms in IRF5, IRAK1, and TNFAIP3 with human disease, and the upregulation of TLRs in SLE patients." (PMID 20886024, 2010). "In systemic lupus erythematosus (SLE),miR-146a expression was decreased, while IRAK1 and TRAF6 expressionremained unchanged." (PMID 41552448, 2026).
lupus (continued). "We found that JP could inhibit the activation of peritoneal macrophages in MRL/lpr lupus mice by regulating the IRAK1-NF-κB signaling pathway to achieve a certain therapeutic effect on SLE." (PMID 31781262, 2019). "Therefore, in this experiment, we selected primary cells such as MRL/lpr lupus mouse peritoneal macrophages as the research object and explored the mechanism of action between SLE and IRAK1 signaling pathway from the cellular level." (PMID 31781262, 2019). "The expressions of TNF-α and IL-6 in lupus patients are generally higher than that in healthy people, and studies have reported that the lack of IRAK1 could reduce the production of IL-6 and TNF-α." (PMID 32760274, 2020).